IST1 (IST1 factor associated with ESCRT-III)
Description:
ESCRT-III-like protein involved in cytokinesis, nuclear envelope reassembly and endosomal tubulation. Is required for efficient abscission during cytokinesis. Involved in recruiting VPS4A and/or VPS4B to the midbody of dividing cells. During late anaphase, involved in nuclear envelope reassembly and mitotic spindle disassembly together with the ESCRT-III complex: IST1 acts by mediating the recruitment of SPAST to the nuclear membrane, leading to microtubule severing. Recruited to the reforming nuclear envelope (NE) during anaphase by LEMD2. Regulates early endosomal tubulation together with the ESCRT-III complex by mediating the recruitment of SPAST.
Synonyms: CHMP8; OLC1; formerly KIAA0174
Tractability: Antibody: its Gene Ontology location is reachable by antibodies, with high confidence. PROTAC: ubiquitination databases record sites on it; its protein half-life has been measured.
Gene: Protein-coding gene on chromosome 16 (71,845,996 to 71,931,199, forward strand). Ensembl gene ENSG00000182149.
Subcellular location: Cytoplasmic vesicle; Cytoplasm, cytoskeleton, microtubule organizing center, centrosome; Midbody; Nucleus envelope
Subcellular location (Human Protein Atlas): Vesicles
Pathways (Reactome):
Cell Cycle: Sealing of the nuclear envelope (NE) by ESCRT-III
Immune System: Neutrophil degranulation
Gene Ontology:
Molecular function: cadherin binding; MIT domain binding; protein binding; protein domain specific binding; protein-containing complex binding
Biological process: cell division; cytoskeleton-dependent cytokinesis; establishment of protein localization; intracellular protein localization; midbody abscission; positive regulation of proteolysis; ESCRT III complex disassembly; multivesicular body assembly; protein transport
Cellular component: centrosome; chromatin; cytoplasmic vesicle; cytosol; endoplasmic reticulum-Golgi intermediate compartment; extracellular exosome; Flemming body; midbody; nuclear envelope; azurophil granule lumen; extracellular region
Genetic constraint (gnomAD): Loss-of-function variants: 8 observed, 15.65 expected, observed/expected ratio (o/e) 0.51, 90% interval 0.3 to 0.92. The upper end of that interval is the gene's LOEUF score, 0.92, which puts it in group 3 of 6, group 1 being the genes least tolerant of losing a copy. Missense variants: 280 observed, 270.42 expected, observed/expected ratio (o/e) 1.04, 90% interval 0.94 to 1.14. Synonymous variants: 107 observed, 101.06 expected, observed/expected ratio (o/e) 1.06, 90% interval 0.9 to 1.24.
Homologues: Orthologues: chimpanzee IST1 (99% identical), macaque IST1 (97% identical), dog IST1 (97% identical), guinea pig IST1 (97% identical), rabbit IST1 (95% identical), mouse Ist1 (95% identical), rat Ist1 (95% identical), pig IST1 (90% identical), zebrafish ist1 (75% identical), tropical clawed frog ist1 (74% identical), tropical clawed frog XB5993342 (61% identical), Drosophila melanogaster Ist1 (53% identical), and 1 more.
Diseases named in the same sentence as IST1 in open-access papers:
IST1 is named in the same sentence as 30 diseases in open-access papers, as found by Europe PMC text mining. Sharing a sentence is not in itself a finding about the gene and the disease. The quoted sentences say what the papers report.
colorectal cancer (3 papers, 2017 to 2023). A primary or metastatic malignant neoplasm that affects the colon or rectum. "Human IST1 is also known as overexpressed in lung cancer 1 (OLC1), since it is overexpressed in many tumours, such as lung and colorectal cancer." (PMID 31412999, 2019).
gastric cancer (3 papers, 2015 to 2017). A primary or metastatic malignant neoplasm involving the stomach. "The statistical analysis the normalized peak lists shows 21 chemical shift peaks were significantly vary between the gastric cancer cell lines (SNU484, MKN28, IST1, and NUGC3) and normal gastric cell line (HS738)." (PMID 27611679, 2016). "The independent panel of 22 gastric cancer cell lines comprised: Kato III, NCI-N87, Hs746T,AZ521, Fu97, IM95, Ist1, MKN1, MKN45, MKN74,MKN28, MKN45,TMK1,SCH,YCC1, YCC3, YCC6, YCC7, YCC10, YCC11 and YCC16." (PMID 26493335, 2015). "The gastric cancer cell lines that can form spheroids were SNU484, NUGC 3, MKN28 and IST1." (PMID 27611679, 2016).
Alzheimer disease (1 paper, 2022). A progressive, neurodegenerative disease characterized by loss of function and death of nerve cells in several areas of the brain leading to loss of cognitive function such as memory and language. "MAPT protein (the hallmark pathology in Alzheimer’s disease) aggregation inhibits the expression of IST1 through the CEBPB-ANP32A-INHAT pathway, which hinders the formation of the ESCRT-III complex, inhibits the fusion of autophagosomes and lysosomes, and leads to autophagy disorder." (PMID 35463448, 2022).
bladder cancer (1 paper, 2025). "This analysis showed that high expression of genes encoding two proteins, CATC and SPB10, was significantly associated with poorer survival in bladder cancer, while IST1 expression was linked to better survival." (PMID 41463032, 2025).
giant cell arteritis (1 paper, 2023). "Indeed, immunohistochemistry of temporal artery biopsies of giant cell arteritis (GCA) patients showed bright IST1 labeling of CD68+ macrophages and vimentin+ fibroblasts." (PMID 37200023, 2023).
glioma (1 paper, 2021). A benign or malignant brain and spinal cord tumor that arises from glial cells (astrocytes, oligodendrocytes, ependymal cells). "Combining the two databases, we noticed that MVB12A, VPS25, CHMP2A, and IST1 were highly expressed in glioma." (PMID 34863175, 2021). "For instance, MVB12A, VPS25, CHMP2A, and IST1 were significantly upregulated in glioma, whereas VPS36 and CHMP1B were significantly downregulated." (PMID 34863175, 2021).
hearing loss (1 paper, 2021). "Taken together, our findings make IST1 an excellent candidate gene for nonsyndromic hearing loss." (PMID 33924653, 2021).
pancreatic diseases (1 paper, 2021). "Some of them were upregulated in patients with other pancreatic diseases, such as HBB, HBA1, and KRT16 proteins, while some were upregulated only in PC groups (i.e. ALIX, GPRC5B, SDCBP, and IST1), highlighting their potential diagnostic value." (PMID 34026608, 2021). "Among the four upregulated proteins in PC group, three were interacted with each other (ALIX, SDCBP and IST1), and the fold change of ALIX expression in PC vs. other pancreatic diseases was higher compared with both SDCBP and IST1." (PMID 34026608, 2021). "Four proteins were significantly higher in PC compared with other pancreatic diseases, including PDCD6IP (also known as ALIX), GPRC5B, SDCBP, and IST1." (PMID 34026608, 2021).
IST1 also shares sentences with these, for which no sentence is quoted: tumor (4 papers); cancer (3); adenocarcinoma (2); esophageal squamous cell carcinoma (2); lung carcinoma (2); Anxiety (1); breast carcinoma (1); carcinoma in situ (1); dysplasia (1); esophageal cancer (1); fibrosarcoma (1); gastric adenocarcinoma (1); gastric mucinous adenocarcinoma (1); gastritis (1); invasive carcinoma (1); neurodevelopmental disorder (1); pancreatic carcinomas (1); proteopathy (1); sensorineural hearing loss (1); squamous cell carcinoma (1); stomach tumors (1); ulcer (1).